WDHD1 (WD repeat and HMG-box DNA binding protein 1)
Description:
Core replisome component that acts as a replication initiation factor. Binds directly to the CMG complex and functions as a hub to recruit additional proteins to the replication fork.
Synonyms: And-1; AND1; CTF4; CHTF4
Tractability: Small molecule: a structure with a bound ligand is known. PROTAC: UniProt records ubiquitination sites on it; ubiquitination databases record sites on it.
Target class: Reader; Epigenetic regulator; Methyl-lysine/arginine binding protein; WDR domain
Gene: Protein-coding gene on chromosome 14 (54,938,949 to 55,027,450, reverse strand). Ensembl gene ENSG00000198554.
Subcellular location: Nucleus, nucleoplasm
Subcellular location (Human Protein Atlas): Nucleoplasm
Gene Ontology:
Molecular function: protein binding; chromatin binding; DNA binding; nucleic acid binding
Biological process: DNA repair; DNA-templated DNA replication; mitotic cell cycle
Cellular component: nucleoplasm; cytoplasm; nuclear replication fork
Genetic constraint (gnomAD): Loss-of-function variants: 87 observed, 112.6 expected, observed/expected ratio (o/e) 0.77, 90% interval 0.65 to 0.92. The upper end of that interval is the gene's LOEUF score, 0.92, which puts it in group 3 of 6, group 1 being the genes least tolerant of losing a copy. Missense variants: 1,214 observed, 1,239.8 expected, observed/expected ratio (o/e) 0.98, 90% interval 0.93 to 1.03. Synonymous variants: 391 observed, 405.22 expected, observed/expected ratio (o/e) 0.96, 90% interval 0.89 to 1.05.
Homologues: Orthologues: chimpanzee WDHD1 (99% identical), macaque WDHD1 (98% identical), dog WDHD1 (90% identical), pig WDHD1 (89% identical), rabbit WDHD1 (89% identical), mouse Wdhd1 (83% identical), rat Wdhd1 (81% identical), guinea pig WDHD1 (79% identical), tropical clawed frog wdhd1 (65% identical), zebrafish wdhd1 (60% identical), Drosophila melanogaster Ctf4 (24% identical), Caenorhabditis elegans ctf-4 (23% identical).
Diseases named in the same sentence as WDHD1 in open-access papers:
WDHD1 is named in the same sentence as 41 diseases in open-access papers, as found by Europe PMC text mining. Sharing a sentence is not in itself a finding about the gene and the disease. The quoted sentences say what the papers report.
esophageal cancer (7 papers, 2019 to 2024). A primary or metastatic malignant neoplasm involving the esophagus. "The identification of WDHD1 as a central gene linked to esophageal squamous cell carcinoma (ESCC) highlights its crucial involvement in the onset of esophageal cancer." (PMID 37569867, 2023). "Notably, several studies have implicated WDHD1 in the development and progression of diverse tumor types, including esophageal carcinoma, pulmonary carcinoma, and breast carcinoma." (PMID 37569867, 2023). "WDHD1 is highly expressed in patients who suffer from pancreatic, liver, breast, lung and esophageal cancers, and can be used as a tumor marker." (PMID 39935706, 2024). "WDHD1 has been identified as a key gene in the occurrence of esophageal cancer, but there are few related researches on the mechanism of WDHD1 causing esophageal cancer." (PMID 35422862, 2022). "Currently, studies have proved that WDHD1 is the central gene for the occurrence and development of esophageal cancer." (PMID 35422862, 2022). "After phosphorylated by AKT, WDHD1 may promote the occurrence of esophageal cancer by regulating cell cycle and inducing DNA replication." (PMID 35422862, 2022). "This manuscript reviews the relationship between WDHD1 and esophageal cancer." (PMID 35422862, 2022). "We think that WDHD1 may be a tumor factor that plays an irreplaceable role in the occurrence of esophageal cancer." (PMID 35422862, 2022). "WDHD1 is a key post-transcriptional regulator of centromeric, and consequently genomic, integrity and its overexpression has been identified as biomarker of acute myeloid leukemia, and lung and esophageal carcinomas." (PMID 31277598, 2019). "However, the effect of WDHD1 on esophageal cancer is rarely reported." (PMID 35422862, 2022). "Numerous studies have demonstrated that WDHD1 can affect the growth of esophageal cancer by regulating the PI3K/AKT pathway during the cell cycle, WDHD1 in nasopharyngeal cancer, and ITGAV in the management of the NPC cell cycle." (PMID 38980253, 2024). "Significantly, WDHD1 acts as a target downstream of the PI3K/AKT pathway, playing a significant role in the progression of esophageal cancer by participating in abnormal cellular regulation through multiple downstream targets of AKT." (PMID 37569867, 2023). "To sum up, we have fully explored the activation process of PI3K/AKT, and we want to put forward the viewpoint that WDHD1, as the downstream target of PI3K/AKT pathway, is involved in the occurrence of human esophageal cancer." (PMID 35422862, 2022). "By reading relevant literature, we concluded that WDHD1, as the downstream target of the PI3K/AKT pathway, is involved in the occurrence of esophageal cancer." (PMID 35422862, 2022). "Some scholars identified the central genes related to the pathogenesis of esophageal cancer through weighted gene coexpression network analysis (WGCNA), including WDHD1, whose expression in esophageal cancer tissue increased significantly." (PMID 35422862, 2022). "WD repeat and HMG-box DNA binding protein 1(WDHD1), as a key gene, plays an important role in the occurrence of esophageal cancer." (PMID 35422862, 2022). "This is consistent with previous studies that have demonstrated elevated WDHD1 mRNA expression in various types of cancer, including LUAD, esophageal cancer, CHOL, colorectal cancer, and laryngeal squamous cell carcinoma (LSCC), while showing no significant expression in normal tissues." (PMID 37759234, 2023). "The study also showed that the survival time of WDHD1 gene-positive esophageal cancer patients was shorter than that of WDHD1 gene-negative esophageal cancer patients through tissue chip experiments." (PMID 35422862, 2022).
cervical cancer (5 papers, 2018 to 2023). A primary or metastatic malignant neoplasm involving the cervix. "For instance, in cervical cancer, WDHD1 has been identified as a critical gene associated with lymph node metastasis." (PMID 37759234, 2023). "Knockdown of WDHD1 in cervical cancer cells expressing the E7 oncogene resulted in a significant decrease in cell cycle proliferation and DNA synthesis, thereby hindering HPV-induced carcinogenesis." (PMID 37759234, 2023). "WDHD1 is highly expressed in cervical cancer cells and plays an important role in the initiation of cervical cancer induced by HPV E7." (PMID 37569867, 2023). "For example, studies have confirmed that WDHD1 is upregulated in cervical cancer cells, and knocking out WDHD1 in these cells leads to G1 stagnation, which affects the cell cycle and cellular replication." (PMID 32426268, 2020). "Moreover, WDHD1 has demonstrated its importance in various types of cancers, including lung cancer, cholangiocarcinoma, cervical cancer, and breast cancer." (PMID 37569867, 2023). "WDHD1 is a potential therapeutic target in cervical cancer progression and metastasis." (PMID 37569867, 2023). "We showed that four miRNAs (miR-502, miR-145, miR-142, and miR-33b) are independent and common prognostic biomarkers for patients with cervical cancer, and seven proteins (CXCL12, IGF1, PTPRC CDH5, RAD51B, REV3L, and WDHD1) are key genes significantly related to lymph node metastasis." (PMID 32457603, 2020).
lung cancer (4 papers, 2020 to 2023). A malignant neoplasm involving the lung. "WDHD1 overexpression is inversely associated with the overall survival of lung cancer patients, indicating its potential prognostic relevance." (PMID 37569867, 2023). "knocked down the expression of WDHD1, tested the radiotherapy sensitivity of non‐small cell lung cancer cells (NSCLC) by clonal formation assay, flow cytometry, comet assay, and immunofluorescence and verified it in a vivo xenograft tumor model." (PMID 36345604, 2023).
breast carcinoma (3 papers, 2021 to 2023). "For breast cancer, it has been reported that WDHD1 plays a crucial role in sustaining the survival of PTEN-inactive TNBC cells by mediating a high demand for protein translation." (PMID 37759234, 2023). "Depletion of WDHD1 makes cells highly responsive to different chemotherapy drugs, such as PARP inhibitors, which are frequently used in clinics to treat patients with prostate, ovarian, and breast cancer." (PMID 37569867, 2023).
cholangiocarcinoma (3 papers, 2023). A carcinoma that arises from the intrahepatic biliary tree (intrahepatic cholangiocarcinoma) or from the junction, or adjacent to the junction, of the right and left hepatic ducts (hilar cholangiocarcinoma). "Additionally, researchers have also observed a higher WDHD1 expression in PTEN-inactive TNBC cells, human papillomavirus (HPV)-16 oncogene E7-expressing spontaneously immortalized human foreskin keratinocytes, cholangiocarcinoma cell lines, and MEL cells." (PMID 37759234, 2023).
laryngeal carcinoma (2 papers, 2023). Carcinoma that arises from the laryngeal epithelium. "In laryngeal cancer, high WDHD1 expression was observed in patients with lymph node metastases or higher stages." (PMID 37759234, 2023). "Overall, WDHD1 represents a promising therapeutic target for laryngeal cancer." (PMID 37569867, 2023).
laryngeal squamous cell carcinoma (2 papers, 2023). A squamous cell carcinoma that arises from the larynx. "Our research group was surprised to find that WDHD1 was also highly expressed in laryngeal squamous cell carcinoma." (PMID 36345604, 2023).
nasopharyngeal carcinoma (2 papers, 2023). A carcinoma arising from the nasopharyngeal epithelium. "Comprehensive analysis showed that WDHD1 is highly expressed in nasopharyngeal carcinoma (NPC) tissues, and it may affect cell apoptosis by regulating the expression of ITGAV." (PMID 36345604, 2023).
non-small cell lung carcinoma (2 papers, 2023). A group of at least three distinct histological types of lung cancer, including non-small cell squamous cell carcinoma, adenocarcinoma, and large cell carcinoma. "Additionally, suppressing WDHD1 expression leads to increased radiosensitivity in non-small cell lung carcinoma (NSCLC) cells, suggesting its effect on the modulation of therapeutic response." (PMID 37569867, 2023).
ovarian carcinoma (2 papers, 2021 to 2023). A malignant neoplasm originating from the surface ovarian epithelium. "WDHD1 can activate fanconi anemia (FA) signaling in ovarian cancer and leads to cisplatin resistance." (PMID 37569867, 2023). "Further investigation is warranted to explore the potential of inhibiting WDHD1 as a promising therapeutic approach to overcome platinum drug resistance in ovarian cancer." (PMID 37569867, 2023). "For example, inhibitors of WDHD1 can enhance the responsiveness of platinum-resistant ovarian cancer cells to platinum-based medications." (PMID 37569867, 2023). "Additionally, phosphorylation of WDHD1 by the ATR is important for enhancing therapeutic outcomes in platinum-resistant ovarian cancer." (PMID 37569867, 2023).
pancreatic adenocarcinoma (2 papers, 2021 to 2023). "By applying weighted correlation network analysis (WGCNA) to expression profiles obtained from The Cancer Genome Atlas (TCGA), a comprehensive gene interaction network was established, revealing multiple genes, including WDHD1, with potential implications in pancreatic adenocarcinoma." (PMID 37569867, 2023). "Here, we employed WGCNA to identify novel hub genes including PKMYT1, WDHD1, ASF1B, and RAD18, and proposed for the first time their oncogenic roles during pancreatic adenocarcinoma progression." (PMID 35047023, 2021).
pancreatic cancer (2 papers, 2023 to 2026). "In summary, WDHD1 is an important potential diagnostic marker and therapeutic target for pancreatic cancer." (PMID 37569867, 2023). "WDHD1 expression was significantly increased in pancreatic cancer and had a 10% amplification mutation frequency, suggesting its role as an oncogene." (PMID 37569867, 2023). "In vivo xenograft models further validated that WDHD1 knockdown suppressed the growth of pancreatic cancer cells." (PMID 42041705, 2026). "WDHD1 expression was significantly elevated in pancreatic cancer cells and tissues compared to normal counterparts." (PMID 42041705, 2026). "In conclusion, E2F1 promotes pancreatic cancer cell proliferation and cell-cycle progression by upregulating WDHD1, which in turn enhances the expression of the CDK4-cyclin D1 complex." (PMID 42041705, 2026). "This study investigated the mechanisms by which WDHD1 contributes to pancreatic cancer progression." (PMID 42041705, 2026). "In addition, the high expression of WDHD1 can promote DNA replication and DNA repair in cancer cells, thus inducing chemotherapy resistance of pancreatic cancer." (PMID 37569867, 2023). "WD repeat and HMG-box DNA-binding protein 1 (WDHD1) has been identified as a crucial oncogene in various tumors, but its role in pancreatic cancer remains unexplored." (PMID 42041705, 2026).
acute liver failure (1 paper, 2026). Rapid deterioration of liver function causing encephalopathy and coagulopathy. "Here, we report bi-allelic hypomorphic variants in WDHD1 as a cause of MPD with a broad spectrum of additional abnormalities, including acute liver failure, in 17 subjects from 14 families." (PMID 41962535, 2026).
bladder cancer (1 paper, 2024). "This shows that by determining the range of WDHD1 expression, we can provide patients with bladder cancer with a whole new method of clinical treatment." (PMID 38980253, 2024). "The results revealed that high WDHD1 expression was supportive of increased bladder cancer cells’ capacity for invasive migration." (PMID 38980253, 2024). "According to our TIDE results, the immune treatment of bladder cancer is ineffective in cases of high expression of WDHD1." (PMID 38980253, 2024). "Finally, we performed an invasive migration experiment to investigate the effect of WDHD1 expression on bladder cancer cells for invasiveness and migration." (PMID 38980253, 2024). "In conclusion, this is the first investigation into WDHD1 and bladder cancer." (PMID 38980253, 2024). "Therefore, we hypothesize that elevated WDHD1 expression may impact immune cells like CD8+ T cells and secrete IL-6 and TGF-β, which may result in people with bladder cancer having a dismal prognosis." (PMID 38980253, 2024).
brain tumors (1 paper, 2023). "Regarding head, neck, lung, and brain tumors, high WDHD1 expression was associated with shorter OS in LUAD (p = 0.001) and LGG (p < 0.001)." (PMID 37759234, 2023).
gallbladder cancer (1 paper, 2024). "Research has also indicated that microRNA-494 may impede upper-intercutancy transformation by WDHD1 expression in gallbladder cancer by lowering its level of expression." (PMID 38980253, 2024).
glioblastoma (1 paper, 2023). The most malignant astrocytic tumor (WHO grade IV). "The analysis revealed a significant upregulation of WDHD1 protein in BRCA, COAD, glioblastoma multiforme (GBM), HNSC, KIRC, LIHC, LUAD, PAAD, and UCEC when compared to normal tissues." (PMID 37759234, 2023).
glioma (1 paper, 2024). A benign or malignant brain and spinal cord tumor that arises from glial cells (astrocytes, oligodendrocytes, ependymal cells). "Our results demonstrated a correlation between high levels of WDHD1 expression and positive CXCL10 and CXCL5 in gliomas." (PMID 38980253, 2024).
hypospadias (1 paper, 2020). Hypospadias is the displacement of the urethral meatus on the ventrum of the penis. "Within the cis-flanking region of cg07509211, we identified significant causal relationship of hypospadias with expression of WDHD1, a WD repeat and HMG-box DNA binding protein that acts as a transcription factor in the mesodermal commitment pathway." (PMID 32728162, 2020).
lung adenocarcinoma (1 paper, 2020). A carcinoma that arises from the lung and is characterized by the presence of malignant glandular epithelial cells. "This study aimed to explore the role of the ubiquitin ligase WD repeat and HMG-box DNA binding protein 1 (WDHD1) in regulating cisplatin sensitivity in lung adenocarcinoma (LUAD)." (PMID 32426268, 2020).
uterine corpus endometrial carcinoma (1 paper, 2023). A endometrial carcinoma (disease) that involves the body of uterus. "Furthermore, in uterine corpus endometrial carcinoma (UCEC) and liver hepatocellular carcinoma (LIHC), WDHD1 expression was significantly associated with higher histological grades and pathological stages." (PMID 37759234, 2023).
viral infection (1 paper, 2023). "Also, as a tumor closely associated with viral infection, the relationship between WDHD1 and HBV infection in LIHC deserves to be explored in depth." (PMID 37759234, 2023).